OLFM4 (olfactomedin 4)
Diseases named in the same sentence as OLFM4 in open-access papers (continued):
Sharing a sentence is not in itself a finding about the gene and the disease.
tumor (continued). "We confirmed that GFP+ cells expressed high levels of GFP, Notch1, Nrarp, Hes1 and Olfm4, the three-latter representing direct Notch targets, indicating that the Notch pathway is indeed active in Notch1+ tumour cells." (PMID 30696875, 2019). "As expected, the results indicated upregulation of OLFM4 expression in tumor tissue compared to normal tissue in this country." (PMID 29511474, 2017). "OLFM4, which is found in stage 2 vs normal and stage 2 vs stage 1 experiments is known to be expressed in inflamed colonic epithelium, promotes tumour growth and facilitates cell adhesion." (PMID 28974751, 2017). "Low expression of OLFM4 was also associated with high tumor FIGO stage and poor tumor differentiation." (PMID 26871282, 2016). "Results demonstrated that OLFM4 was upregulated in EGC tumor sections compared with adjacent non-tumor tissues (P<0.001), and was mainly distributed within the cytoplasm of the tumor cells." (PMID 27294866, 2016). "Results demonstrated that significant correlation between LNM and larger tumor size (P=0.049), poorly differentiated carcinoma (P=0.039), intravascular tumor thrombi (P=0.028), as well as reduced OLFM4 expression (P<0.001)." (PMID 27294866, 2016). "We further constructed a nomogram that integrated the predictive factors including tumor size, differentiation and OLFM4 expression to provide a quantitative method for better predicting the LNM in EGC." (PMID 27294866, 2016). "The frequency of tumor formation in the liver, lung, and pancreas was also significantly increased in older Olfm4-knockout mice." (PMID 26581960, 2015). "OLFM4 is an anti-apoptotic factor that promotes tumor growth and facilitates cell adhesion, probably via interacting with cell surface lectins and cadherin." (PMID 26572220, 2015). "One such gene is olfactomedin 4, a protein expressed in bone marrow cells, tumor cells, and intestinal epithelium but found to be highly over-represented in our ARDS patient samples." (PMID 25849954, 2015). "Forced expression of OLFM4 in cancer cells has been reported to show anti-apoptotic action and promote tumour growth in vivo." (PMID 24495253, 2014). "The transwell migration and invasion assay indicated that knockdown of OLFM4 enhanced the tumour cell capacity for migration and invasion." (PMID 24495253, 2014). "Aberrant expression of OLFM4 has been detected in several types of tumours, especially of the digestive system." (PMID 24495253, 2014). "Olfm4 is a secreted anti-apoptotic factor, which has been reported to be over-expressed in a variety of tumours." (PMID 25010414, 2014). "It has been suggested that OLFM4 is involved in cellular process such as apoptosis and tumor growth." (PMID 22471589, 2012). "Consistent with the results of qRT-PCR, significant reduction of OLFM4 protein was also observed in tumor xenografts by IHC (P < 0.01)." (PMID 22471589, 2012). "To further assure OLFM4 expression is indeedly silenced after subcutaneous injection of nude mice, we also evaluated OLFM4 expression in tumor xenografts using qRT-PCR and IHC." (PMID 22471589, 2012). "On the contrary, weak brown staining was observed in tumor xenografts of OLFM4 knockdown cells-injected group." (PMID 22471589, 2012). "Furthermore, M-HIFU-induced modifications in the tumor microenvironment can amplify the anti-tumoral effect targeting OLFM4+ CSCs.." (PMID 39861713, 2025). "Additionally, elucidating the complex interplay between OLFM4+ CSCs and immune cells within the tumor microenvironment is crucial for tailoring DC vaccine strategies to maximize their efficacy." (PMID 39861713, 2025). "Second, while we have identified two CSC markers including SOX9 and OLFM4 at single‐cell resolution and in vitro experiments, in vivo functional validation in animal models to confirm the role of CSCs in tumor initiation, progression, and resistance is still required." (PMID 39950944, 2025).
tumor (continued). "We found that these cells were rarely detected in established organoids but appeared in the early phases of organoid reconstruction from single OLFM4+ cells, raising the possibility that Paneth-like cells can be generated by cell fate conversion in response to alteration in tumor integrity." (PMID 38182890, 2024). "The upregulation of OLFM4 expression in the CR group suggests that environmental conditions at the tumor site, including bacterial infections other than Hp and the associated inflammation, may contribute to the response to eradication therapy." (PMID 36831547, 2023). "In this study, we show that the absence of miR-34a in IECs results in changes of the cellular composition of the small intestine, i.e. an increase of Paneth cells and Olfm4-positive stem cells, and an increased tumor burden as well as decreased survival in ApcMin/+ mice." (PMID 36147476, 2022). "However, in our study, gender differences were found for OLFM4 level and tumor size in HCC patients." (PMID 34912753, 2021). "Several studies have investigated the role of OLFM4 in tumor differentiation." (PMID 31923206, 2020). "Previous miRNA microarray studies revealed that miR-486 could regulate tumor progression and the OLFM4 antiapoptotic factor in GC." (PMID 29879180, 2018). "To determine whether the lysozyme expression and stem cell phenotypes were maintained in tumour tissue, we analysed lysozyme and OLFM4 expression in these tumours." (PMID 28003334, 2017). "Microinvasion in tumor was observed in the DLP tissue of Olfm4-knockout mice at 23 months of age." (PMID 26581960, 2015). "Aberrant expression of OLFM4 has been primarily reported in tumours of the digestive system." (PMID 24495253, 2014). "Moreover, some of tested samples down-regulated the OLFM4 gene, which was recently reported to inhibit apoptotic pathways and to promote tumor cell proliferation." (PMID 23430930, 2013). "Similarly in vitro, OLFM4 mRNA level in tumor xenografts produced by OLFM4 knockdown cells also showed a significant decrease compared with HK control tumors xenografts (P < 0.01)." (PMID 22471589, 2012). "Moreover, we also performed subcutaneous tumor formative assay in nude mice to evaluate the growth suppression effect of down-regulated OLFM4 in vivo." (PMID 22471589, 2012). "Although previous studies have shown that OLFM4 is involved in apoptosis and tumor growth, recent observations also suggest that cell or tissue-specific effects may exist for the OLFM4 gene." (PMID 22471589, 2012). "Whether tumor volume or tumor weight produced by OLFM4 knock down SGC-7901 and MKN45 cells had significantly reduced growth compared with tumors produced in mice injected with HK control-transfected cells (P < 0.01)." (PMID 22471589, 2012). "miR-486-5p was shown to regulate tumor progression and OLFM4 anti-apoptotic factor." (PMID 21864403, 2011). "Future research will focus on exploring how OLFM4 affects the interactions between HNSCC cells and immune cells, such as tumor-associated macrophages and T lymphocytes, which are the main components in TME and are involved in tumor ferroptosis and chemoresistance." (PMID 40422535, 2025). "Interestingly, OLFM4 level has a significant correlation to tumor size (R2 = 0.4646, P < 0.0001)." (PMID 34912753, 2021). "Furthermore, low OLFM4 expression, but not poor tumor differentiation, was independently associated with LNM in advanced EAC in the present study." (PMID 31283789, 2019). "In the subcutaneous tumor model, lymphocytes from mice treated with the combination of DCs[SC] and M-HIFU demonstrated enhanced lysis of OLFM4-positive target cells, which was further amplified by combined treatment with DCs[SC]." (PMID 39861713, 2025). "In the subcutaneous tumor model, mice treated with M-HIFU had a significantly higher number of OLFM4-specific IFN-γ-producing splenocytes than those treated with T-HIFU or N.C.." (PMID 39861713, 2025).
tumor (continued). "We found that CSCs expressed high levels of tumor stemness genes (PROM1, CD24, CD47, ANPEP, ALDH1A1, OLFM4, and SOX9), and demonstrated a high cancer stemness score, along with activation of the cancer driver genes EGFR and ERBB2." (PMID 39950944, 2025). "Another study found OLFM4 to be a key marker overexpressed in human incomplete GIM samples, and that this overexpression promoted tumor-like behaviors through Wnt/β-catenin signaling." (PMID 40000871, 2025). "OLFM4 is a secreted glycoprotein belonging to the OLFM family and a marker of intestinal stem cells which is increased in the early stages of tumor initiation." (PMID 39695857, 2024). "IFI27, LCN2, GAST, and SERPINA1 were downregulated after NACT in tumor cells, while OLFM4, MRPS35, MMP1 and MED21 were upregulated in tumor cells." (PMID 36474268, 2022). "Genes associated with proliferation such as proliferating cell nuclear antigen (PCNA), prominin 1 (PROM1), HOP homeobox (HOPX), and olfactomedin 4 (OLFM4) were also upregulated in LPS treated IBD intestinal organoids and tumor enteroids." (PMID 35884586, 2022). "We also found that OLFM4 has a high predictive value for diagnosing HCC and is closely correlated to tumor size." (PMID 34912753, 2021). "OLFM4, SPINK8, CRYAB, KCNMA1, TFAP2B, and TFF1 were significantly upregulated during tumor progression in P8‐2 CTCs." (PMID 33377642, 2020). "The expression of OLFM4, EPHB2, and ASCL2 was relatively restricted to the basal region of tumor glands in the GA with basal LGR5 expression, but the expression of these markers was diffuse in the GA with a diffuse LGR5 expression pattern." (PMID 24340024, 2013). "Our results also observed that knock-down of OLFM4 did not influence the rate of apoptosis and caspase-3 and 9 activations in OLFM4 knockdown cells, suggesting that apoptosis might not be the mechanism underlying the inhibition of tumor growth." (PMID 22471589, 2012). "In summary, our findings establish OLFM4 as a critical oncogenic driver in HNSCC progression and prognosis, demonstrating that its upregulation promotes tumor aggressiveness through enhanced proliferation, migratory, and invasive capacities while simultaneously conferring cisplatin resistance." (PMID 40422535, 2025). "Importantly, we found that inflammatory CAFs (iCAFs) enhance tumor stemness by upregulating SOX9 and OLFM4, contributing to drug resistance and cell proliferation through the AREG‐ERBB2 signaling pathway." (PMID 39950944, 2025). "Interestingly, the spatial clusters C3 and C5 both expressed high levels of stem cell markers OLFM4, SOX9, and ANPEP, corresponding to the metaplasia and tumor regions, respectively." (PMID 39950944, 2025). "Notably, we also found that IL11+CD10+ iCAFs were a key component of CSC niche that drive tumor stemness in CSCs by upregulating the expression of SOX9 and OLFM4, leading to drug resistance via the AREG‐ERBB2 signaling pathway." (PMID 39950944, 2025). "Importantly, reduced mRNA expression of LGR5, OLFM4, ASCL2 and EPHB2 was also observed in HG primary tumours in the TCGA dataset." (PMID 40473896, 2025). "And now based on gene expression patterns, it further indicated that lymph node metastatic tumor cells are more likely originated from OLFM4+SOX9+ C-type cells (PT-b), but not from OLFM4+SOX9- C-type cells (PT-a) in the primary tumor." (PMID 35974387, 2022). "For instance, GBC9-MT showed elevated expression of CD24 (immune checkpoint in promoting immune evasion) and IGFBP2 (metabolic checkpoint in promoting tumor growth), and GBC10-MT displayed cancer stem cell signature (OLFM4) and enhanced cell migration (e.g., CLDN3, CEACAM5)." (PMID 36198671, 2022). "Other intestinal stem cell markers and genes associated with proliferation, notably proliferating cell nuclear antigen (PCNA), prominin 1 (PROM1), HOP homeobox (HOPX), and olfactomedin 4 (OLFM4), were also increased in LPS-treated IBD intestinal organoids and tumor enteroids." (PMID 35884586, 2022).
tumor (continued). "OLFM4 has high predictive capacity as a biomarker for HCC and is closely correlated to tumor size." (PMID 34912753, 2021). "OLFM4 has high predictive capacity as a biomarker for HCC and closely correlates to tumor size." (PMID 34912753, 2021). "In addition, the upregulation of OLFM4 was often detected in highly differentiated and early-stage CRC, while in some poorly differentiated late tumor-node-metastasis stage and metastatic CRC, downregulation or no expression was more frequently detected." (PMID 33622275, 2021). "Furthermore, OLFM4 has been shown to inhibit apoptosis-promoting factor GRIM-19 to induce anti-apoptosis and anti-apoptotic effects in tumor cells exposed to stress-inducing factors, such as hydrogen peroxide, tumor necrosis factor-α, and cytotoxic agents." (PMID 31923206, 2020). "OLFM4 staining in epithelial or stromal cells was not significantly correlated with age, gender, N or M classification or tumor localisation." (PMID 28344541, 2017). "The correlation between OLFM4 expression and tumor size was also not observed in immunohistochemical staining." (PMID 27294866, 2016). "Functionally, OLFM4 has been shown to bind to GRIM19 (a cell-death regulatory protein), cadherins and lectins, and could suppress apoptosis and promote tumor growth and invasion." (PMID 25970782, 2015). "OLFM4 was significantly downregulated in metastatic tumor tissue when compared with normal prostate tissue, whereas SHH was significantly upregulated in metastatic tumor tissue when compared with normal prostate tissue (upper row)." (PMID 26581960, 2015). "Knockdown of OLFM4 increased tumour cell proliferation with and without E2 stimulation, suggesting that OLFM4 partially suppresses tumour cell proliferation." (PMID 24495253, 2014). "Studies of OLFM4 in tumourigenesis have mainly focused on gastrointestinal tumours, but the role of OLFM4 in other tumours is not well-known." (PMID 24495253, 2014). "The enhanced anti-tumor effects observed with M-HIFU, including increased OLFM4-specific cytotoxic lymphocyte activity and a higher frequency of IFN-γ-producing splenocytes, indicate its potential as a more effective approach for targeting OLFM4-expressing tumors." (PMID 39861713, 2025). "Although EpCAM, PIGR, OLFM4, and CLDN4 have been previously identified as membrane markers for GC, they did not effectively discriminate between HM and tumor tissue in our patient cohort." (PMID 40868067, 2025). "Negative correlation between OLFM4 and interleukin-8 expression was also observed in EGC tumor samples." (PMID 27294866, 2016).
cancer (71 papers, 2012 to 2026). A tumor composed of atypical neoplastic, often pleomorphic cells that invade other tissues. "OLFM4, a glycoprotein linked to various cancers, enhances CSC stemness and survival, making it an attractive target for DC vaccines." (PMID 39861713, 2025). "Other DSG3-associated cancer-related genes include upregulated OLFM4 (antiapoptotic factor), downregulated ADAMTS1 (antiangiogenic activity), downregulated KRT84 (cancer suppressor in oral SCC) and FLNC." (PMID 38067138, 2023). "The neutrophilic OLFM4+ subset in cancer was investigated in a more recent study using mice in which OLFM4 was selectively deficient in myeloid cells." (PMID 36922564, 2023). "OLFM4 promotes S phase transition in cancer cells as well as being associated with cell adhesion and metastasis." (PMID 25871394, 2015). "In addition, previous studies suggested a role of OLFM4 in immune cells and associate with increased risk of human cancers." (PMID 32509585, 2020). "Moreover, OLFM4 was also highly expressed in colon, breast, and lung cancerous tissues, where it inhibits apoptosis and promotes cancer cell proliferation, suggesting it may serve as a diagnostic marker or a therapeutic target for human cancers." (PMID 32509585, 2020). "This suggests that OLFM4 could serve as a diagnostic marker for human cancers." (PMID 23430930, 2013). "This approach holds particular promise when tissue-specific characteristics of OLFM4+ cancers are identified prior to initiating immunotherapy." (PMID 39861713, 2025). "The expression of KRT18 (p < 0.0001) and OLFM4 (p = 0.0435) in the cancer‐pre subcluster was significantly greater than that in the other subclusters." (PMID 40860436, 2025). "This CRC‐specific marker promotes cancer cell proliferation and metastasis by positively regulating the expression of its downstream gene, olfactomedin 4 (OLFM4)." (PMID 39690143, 2024). "Olfactomedin 4 (OLFM4), an antiapoptotic factor glycoprotein that facilitates cell adhesion, has been shown to be upregulated in various types of cancer and involved in many cellular processes such as cell adhesion, apoptosis, and cell proliferation." (PMID 39766041, 2024). "NF-κB appears to be activated in the DES cancer model based on pathway analysis of altered genes, including Olfm4, which can be up-regulated by NF-κB, among other transcription factors." (PMID 37856394, 2023). "To validate DES cluster 5 as the cancer cell population, we performed OLFM4 immunohistochemistry (IHC)." (PMID 37856394, 2023). "OLFM4 functions in intestinal stem cells and CSCs and is related to cancer progression as a cancer-promoting factor, the features of which are partially similar to those of NANOG." (PMID 36831547, 2023). "Studies using a conventional Olfm4 knockout mouse model have demonstrated that Olfm4 plays critical roles in innate immunity, inflammation, cancers, and obesity." (PMID 37357228, 2023). "HRCA showed remarkably higher expression levels of intestinal stem cell markers (LGR5, OLFM4) and cancer stem cell markers (c-Myc, CD166)." (PMID 37667332, 2023). "Genes with known implications in cancer, such as MMP-13, KRT84, OLFM4, GJA1, AMOT and ADAMTS1, were strongly linked to DSG3 overexpression." (PMID 38067138, 2023). "Staining of adjacent sections for pAKT revealed consistent overlap of pAKT with OLFM4+ cancer regions." (PMID 37856394, 2023). "It is confirmed that OLFM4 contributes to cancer cell proliferation, and HIF1α is involved in this process." (PMID 34912753, 2021). "In the field of cancer research, the tumorigenic function of OLFM4 has been verified in many tumors." (PMID 34650914, 2021). "Recently, evidence confirmed that OLFM4 plays an important role in regulating growth and proliferation of several types of cancer cells." (PMID 34912753, 2021). "Most importantly, we confirmed that OLFM4 contributes to cancer cell proliferation, and HIF-1α is involved in this process." (PMID 34912753, 2021).